ACE (angiotensin I converting enzyme)
Diseases named in the same sentence as ACE in open-access papers (continued):
Sharing a sentence is not in itself a finding about the gene and the disease.
angioedema (continued). "Angiotensin-converting enzyme (ACE) inhibitors inhibit bradykinin degradation and can trigger oral-lingual angioedema in some patients." (PMID 37288434, 2023). "Subsequently, omapatrilat was developed to inhibit both ACE and NEP, however, the drug failed the clinical trial due to the formation of a side effect of angioedema." (PMID 37299008, 2023). "Targeting the ACE C-domain, while preserving the ACE N-domain, combined with NEP inhibition may be as effective as omapatrilat in lowering BP and cardiovascular protection but without injurious endothelial effects that predispose to microvascular leakage implicated in angioedema." (PMID 34304582, 2021). "This study found that ACE inhibitors and DPP-4 inhibitors, which inhibit the degradation of substance P and bradykinin, tended to have different effects on the onset of angioedema in clinical practice." (PMID 34884209, 2021). "In this study, we found that ACE inhibitors and DPP-4 inhibitors that inhibit the degradation of substance P and bradykinin tend to have different effects on the onset of angioedema in clinical practice." (PMID 34884209, 2021). "Bradykinin-mediated angioedema can be further classified as hereditary angioedema (HAE), acquired angioedema, or angiotensin-converting enzyme (ACE) inhibitor-induced angioedema (ACEi-AE)." (PMID 34692327, 2021). "Nevertheless, we wanted to re-iterate the importance of avoiding known triggers of angioedema such as estrogen-containing oral contraceptives or replacement therapy, DPP-IV inhibitors, neprilysin inhibitors, and ACE inhibitors." (PMID 31788005, 2019). "However, ACE-inhibitor caused angioedema can develop in patients without any known risk factors." (PMID 30075570, 2018). "The exclusion criteria for the PARADIGM-HF study included a history of angioedema during treatment with an ACE inhibitor or ARB, and 78 and 22% of participants, respectively, were previously treated with an ACE inhibitor or ARB." (PMID 30283782, 2018). "Second, anti-hypertensive drugs that inhibit bradykinin breakdown, such as angiotensin-converting enzyme (ACE), dipeptidyl peptidase IV (DPPIV) or neprilysin (NEP), can induce angioedema." (PMID 27122021, 2016). "The labeling states that the agent should be used in conjunction with other HF therapies but in place of ACE inhibitors or ARBs and is contraindicated in patients with a history of ACE inhibitor or ARB-induced angioedema." (PMID 26918130, 2015). "Diagnosis is primarily clinical and relies on the presence of non-itchy, non-urticarial swelling in a patient receiving an ACE inhibitor, as there is no definitive laboratory test for ACE inhibitor-induced angioedema." (PMID 41646567, 2026). "ACE inhibitor-related angioedema is one of the most common types of non-histaminergic angioedema encountered in clinical practice." (PMID 41646567, 2026). "Given the overlapping indications and patient populations, angioedema appearing in patients taking both GLP-1 RAs and ACE inhibitors may become increasingly common and present a diagnostic dilemma." (PMID 42194666, 2026). "Systematic screening for this pathogenic variant should probably not be carried out in patients who develop BK-AE on ACE inhibitors unless the patient reports a family history of angioedema." (PMID 41331604, 2025). "There was no recent use of an angiotensin converting enzyme (ACE) inhibitor to suggest ACE-inhibitor-induced angioedema." (PMID 40959346, 2025). "In this patient, several factors strongly supported ACE inhibitor-induced angioedema as the most likely diagnosis, rather than allergic, hereditary, acquired, or idiopathic causes." (PMID 41035577, 2025). "Differences arise due to ARBs not influencing ACE levels and bradykinin breakdown, avoiding side effects like cough and angioedema." (PMID 39776087, 2025). "The absence of allergen exposure, urticarial rash, or infectious symptoms supported a non-histamine-mediated angioedema, most consistent with ACE inhibitor-induced aetiology." (PMID 41035577, 2025).
angioedema (continued). "The acute onset of oropharyngeal swelling without pruritus or urticaria raised concern for ACE inhibitor-induced angioedema." (PMID 41035577, 2025). "Regarding laboratory testing, there are no definitive tests for diagnosing ACE inhibitor-induced angioedema." (PMID 38543146, 2024). "There are no guidelines on the management of patients with ACE inhibitor-induced angioedema and a positive SARS-CoV-2 result." (PMID 38910667, 2024). "Drug-induced angioedema has been reported in the use of beta-lactam antibiotics, non-steroidal anti-inflammatory drugs (NSAIDs), and angiotensin-converting enzyme (ACE) inhibitors." (PMID 38435190, 2024). "It is also important to avoid angioedema triggers in HAE-nC1-INH, such as estrogen-containing oral contraceptives or estrogen replacement therapy, dipeptidyl peptidase-4 (DPP-4) inhibitors, neprilysin inhibitors and ACE inhibitors." (PMID 39654054, 2024). "In cases of angioedema induced by ACE inhibitors, a distinctive feature is the absence of itching or urticaria; the presence of urticaria indicates different underlying causes." (PMID 38543146, 2024). "Three of these patients were also tachycardic, and one, who was not on an ACE inhibitor, exhibited angioedema." (PMID 38047156, 2024). "Angioedema can be triggered by exposure to drugs such as angiotensin-converting enzyme inhibitors (ACE inhibitors), opioid drugs, and nonsteroidal anti-inflammatory drugs (NSAIDs)." (PMID 39130857, 2024). "ACE inhibitor-induced angioedema should be suspected in any patient who is on an ACE inhibitor and develops angioedema without urticaria." (PMID 39654054, 2024). "Individual reports of angioedema secondary to tenecteplase have rarely been described, and to date none have been in a patient not taking an ACE inhibitor." (PMID 39158246, 2024). "In our patient, hereditary angioedema was unlikely given the use of ACE inhibitors prior to admission, lack of personal or family history of angioedema, and a C4 level of 44 mg/dL." (PMID 38910667, 2024). "More studies are needed to investigate the risk of angioedema and other respiratory complications in African Americans infected with SARS-CoV-2 with and without the presence of an ACE inhibitor." (PMID 38910667, 2024). "The diagnosis of ACE-induced angioedema is based on the presence of angioedema without urticaria or pruritis in a patient taking ACE inhibitors." (PMID 38910667, 2024). "However, a case–control study demonstrated that ACE inhibitors and black ethnicity do not seem to have a synergistic action (OR 1.10, 95% CI 0.80–1.51); thus, black ethnicity per se predisposes patients to experience angioedema attacks, regardless of the type of antihypertensive used." (PMID 38543146, 2024). "Several case reports have been documented of patients taking both ACE inhibitors and DPP-IV inhibitors experiencing bradykinin-induced angioedema; however, no single gliptin had been implicated across case reports." (PMID 38957198, 2023). "In the end, the isolated or designed ACE inhibitory peptides or non-peptide-based compounds need to address the hypertensive patients’ real problems: chronic dry cough and angioedema." (PMID 37299008, 2023). "While angioedema induced by ACE inhibitors has been well-documented, angioedema induced by angiotensin receptor blockers (ARBs) has not." (PMID 37213987, 2023). "If the angioedema is the result of an ACE inhibitor, the patient will have normal levels of C1 inhibitor and C4, effectively ruling out the hereditary subtypes." (PMID 38957198, 2023). "It is noteworthy that ACE inhibitors-induced angioedema has bradykinergic characteristics and does not respond to corticosteroids, antihistamines or epinephrine." (PMID 35413921, 2022). "Angioedema is mediated by bradykinin, produced excessively when there is a lack of a C1 inhibitor-angioedema related to ACE inhibitor: decrease in bradykinin degradation." (PMID 36381703, 2022).
angioedema (continued). "This study suggests that the use of ACE inhibitors and DPP-4 inhibitors, which inhibit the degradation of substance P and bradykinin, in the clinic tend to have different effects on the onset of vasoactive peptide-induced angioedema." (PMID 34884209, 2021). "While only recurrences of ACE inhibitor-induced angioedema are described in the literature, our patient did not develop angioedema while being on the drug and had the first occurrence of angioedema one month after the medication was discontinued." (PMID 34917435, 2021). "However, angioedema can also be acquired and is a well-documented side effect of ACE/kininase II inhibitor treatment occurring rarely but more frequently in African American subjects." (PMID 33800422, 2021). "While kinins are involved in the therapeutic action of ACE inhibitors and AT1 receptor blockers, they may also be responsible for some unwanted effects of these drugs, cough and angioedema." (PMID 33800422, 2021). "Tolerance was acceptable with an incidence of angioedema not superior to other drugs used in the indication, including ACE inhibitors." (PMID 33800422, 2021). "In this study, we sought to clarify whether dipeptidyl peptidase-4 (DPP-4) and angiotensin-converting enzyme (ACE) inhibitors that suppress the degradation of substance P and bradykinin are involved in angioedema onset." (PMID 34884209, 2021). "Given our approach, ACE inhibitors and ARB medications were taken by some patients with angioedema categorized as histaminergic or unknown etiology." (PMID 31539333, 2019). "Deleterious variations in genes responsible for the control of BK release, as SERPING1, or its metabolization, as CPN, CPM, angiotensin-converting enzyme (ACE), and neprilysin (MME), are able to increase the amount of BK released or its half-life, leading to or intensifying angioedema episodes." (PMID 30847342, 2019). "Although complement studies are normal in ACE inhibitor-induced angioedema, C1-INH levels should be measured in these patients as the initiation of an ACE inhibitor could unmask HAE or AAE." (PMID 30263036, 2018). "Angiotensin-converting enzyme inhibitor-induced angioedema should be suspected in any patient who is on an ACE inhibitor and develops angioedema without urticaria." (PMID 30263036, 2018). "Unlike histamine mediated, ACE inhibitor-related angioedema can develop at any time during the treatment course." (PMID 30075570, 2018). "Although evidence suggests that icatibant is also effective for the treatment of ACE inhibitor-induced angioedema, this is not an approved indication." (PMID 30263036, 2018). "C3, C4, IgE levels, and C1 esterase inhibitor protein levels were in the normal range; therefore, hereditary angioedema was ruled out and ACE inhibitor induced angioedema diagnosed." (PMID 30075570, 2018). "During the clinical testing phase, the comparison to the ACE inhibitor enalapril revealed a more than three times more frequent occurrence of angioedema (2.17 vs. 0.68%) so that finally this agent was not approved." (PMID 28025602, 2016). "Nonetheless, AT1 blockers should not be applied in patients who have already had an ACE inhibitor induced angioedema." (PMID 28025602, 2016). "For patients having had angioedema induced by ACE inhibitors or sartans, aliskiren does not represent an alternative because this circumstance was classified as contraindication for therapy by the official authorities." (PMID 28025602, 2016). "The high rate of angioedema in hypertensive patients and the non-superiority compared with ACE inhibitor in patients with HF led to the interruption of the clinical development of omapatrilat." (PMID 26637405, 2016). "The incidence of angioedema, was low and similarly distributed in women and men, regardless of the type of ACE-inhibitor taken into account (zofenopril: 0.4 vs. 0.7%; lisinopril: 0.8 vs. 0.8%; ramipril: 0 vs. 0.7%)." (PMID 25364906, 2014).
angioedema (continued). "The incidence of angioedema, was low and similarly distributed in women and men, regardless of the type of ACE-inhibitor taken into account, suggesting no intra-class effect for this adverse drug reaction." (PMID 25364906, 2014). "ACE inhibitor-induced angioedema is not entirely understood, but it is postulated that the use of ACE inhibitors increases bradykinin levels, which is a potent vasodilator." (PMID 24792779, 2014). "Much like CU, the majority of cases involving acquired angioedema, with some exceptions such as ACE-inhibitor angioedema, can be adequately controlled with daily doses of nonsedating antihistamines." (PMID 23282382, 2012). "The incidence rates of angioedema-related events while on an ACE inhibitor were similar in the sitagliptin and non-exposed groups (1.0 and 1.3 per 100 patient-years, respectively)." (PMID 20412573, 2010). "The exact mechanism for ACE inhibitors-induced angioedema is not clear and it is still a matter of discussion." (PMID 20180980, 2010). "For the specific adverse event of angioedema, the incidence rates were 0.06 and 0.08 while on an ACE inhibitor and 0.03 and 0.04 while not on an ACE inhibitor in the sitagliptin and non-exposed groups, respectively." (PMID 20412573, 2010). "Some medications may trigger or worsen angioedema events in patients with HAE and should be avoided including estrogen contraceptives, hormone replacement therapy, and ACE-Inhibitors." (PMID 20667127, 2010). "Some authors reviewing charts of patients presenting angioedema to an emergency department have observed that pruritus was noted only in patients with angioedema not related to the use of ACE inhibitors." (PMID 20180980, 2010). "For patients not on an ACE inhibitor, the numbers of incident angioedema-related events per 100 patient-years were 1.1 in the sitagliptin group and 1.3 in the non-exposed group." (PMID 18954434, 2008). "The total numbers of angioedema-related events per 100 patient-years while a patient was on an ACE inhibitor were also similar in the sitagliptin (1.1) and non-exposed (0.9) groups." (PMID 18954434, 2008). "A lack of response to antihistamines, a history of ACE inhibitor use and the rapid onset of upper airway swelling may be helpful in identifying ACEi-induced angioedema." (PMID 40365500, 2025). "While there is no universally accepted protocol for sequencing therapies in ACE inhibitor-induced angioedema, the availability of C1-INH at our hospital, clinical decision, and published evidence of benefit in bradykinin-mediated angioedema supported its use as an escalation strategy." (PMID 41035577, 2025). "Second, hereditary or acquired C1-inhibitor deficiency was unlikely, as there was no family history, no history of recurrent abdominal pain or childhood onset swelling, and the patient had reached her 80s without prior angioedema outside of ACE inhibitor therapy." (PMID 41035577, 2025). "The exact mechanisms behind ACE inhibitor-induced angioedema are complex and not fully understood." (PMID 38543146, 2024). "ACE inhibitors are generally considered first-line therapy, but some patients may not tolerate them due to adverse effects like cough or angioedema." (PMID 39252272, 2024). "There is no standardized approach for the treatment of ACE inhibitor-induced angioedema." (PMID 38910667, 2024). "While the onset time of angioedema after initiating ACE inhibitor therapy varies among individuals irrespective of gender, some research suggests that women may experience angioedema earlier after beginning treatment compared to men." (PMID 38543146, 2024). "Therefore, ACE inhibitors should be discontinued in all individuals with angioedema without urticaria and are absolutely contraindicated in patients with either HAE or AAE." (PMID 39654054, 2024).
angioedema (continued). "When an ACE inhibitor inhibits a somatic ACE without domain specificity, accumulation of bradykinin is expected and when the accumulation reaches a certain level, it will be translated into chronic dry cough and angioedema." (PMID 37299008, 2023). "Despite the availability of commercial drugs for ACE inhibition, the lower success rates of drugs and prolonged treatment procedures with persistent side effects (angioedema and cough) and with no one-time remedy necessitate the search for natural solutions against it." (PMID 37324400, 2023). "Authors note that this reduction in angioedema events compared to neprilysin inhibitor and ACE inhibitor combination may be due to ARB decreased degradation of ACE and aminopeptidase P compared to ACE inhibitors." (PMID 38957198, 2023). "ACE inhibitor is the major representative trigger of non-IgE-mediated angioedema." (PMID 34445711, 2021). "However, given that both neprilysin and ACE degrade bradykinin, one would predict higher bradykinin levels with omapatrilat than ACE inhibitor therapy, which no doubt accounts for the higher incidence of angioedema with omapatrilat therapy." (PMID 30283782, 2018). "Additionally, while 96% of our study cohort was African American, no patients experienced ACE inhibitor-induced angioedema, suggesting that any concerns for acute onset of this well-known side effect are unfounded." (PMID 28032307, 2016). "However, the exact mechanism for ACE inhibitors-induced angioedema is not clear and it is still a matter of discussion." (PMID 20180980, 2010). "The ACE inhibitor-induced angioedema is not dose related; however, it may occur almost immediately after the first dose, and is class-, but not drug-, specific and is therefore unlikely to be immunologically mediated." (PMID 23282406, 2008). "Therefore, it is of importance to sensitize physicians for this rare and severe, but treatable disease which might be concealed as an ACE inhibitor-induced angioedema or acquired non-histaminergic angioedema." (PMID 30809376, 2019). "Furthermore, although angioedema may occur during the first week of therapy, some patients may have taken the ACE inhibitor without any problem for weeks or months before angioedema develops." (PMID 23282406, 2008). "No angioedema signals were detected for DPP-4 inhibitors; however, a signal was detected for ACE inhibitors (IC: 2.42, 95% confidence interval (CI): 2.19 to 2.65)." (PMID 34884209, 2021). "However, no signal of angioedema was detected with the DPP-4 inhibitors, in contrast to some ACE inhibitors." (PMID 34884209, 2021).